LERFS (lncRNA negative regulator of fibroblast-like synoviocyte migration, SYNCRIP interacting)
Gene: Long non-coding RNA gene on chromosome 9 (62,856,996 to 62,898,904, reverse strand). Ensembl gene ENSG00000234665.
Diseases named in the same sentence as LERFS in open-access papers:
LERFS is named in the same sentence as 3 diseases in open-access papers, as found by Europe PMC text mining. Sharing a sentence is not in itself a finding about the gene and the disease.
LERFS shares sentences with these, for which no sentence is quoted: cancer (1 paper); Graves disease (1); rheumatoid arthritis (1).